LINC00954 (long independently transcribed non-coding RNA 954)
Synonyms: FLJ12334
Gene: Long non-coding RNA gene on chromosome 2 (19,863,616 to 19,885,047, forward strand). Ensembl gene ENSG00000228784.
Diseases named in the same sentence as LINC00954 in open-access papers:
LINC00954 is named in the same sentence as 2 diseases in open-access papers, as found by Europe PMC text mining. Sharing a sentence is not in itself a finding about the gene and the disease. The quoted sentences say what the papers report.
cancer (1 paper, 2024). A tumor composed of atypical neoplastic, often pleomorphic cells that invade other tissues. "As a conclusion, the LINC00954-ORF polypeptide embedded in lncRNA LINC00954 possesses tumor-suppressor features in A549 and PEM-resistant A549 cells and sensitizes PEM-resistant A549 cells to PEM, providing evidence that the LINC00954-ORF polypeptide is a potential anti-cancer agent in LUAD." (PMID 38351332, 2024).
tumor (1 paper, 2024). "Remarkably, the increase of the LINC00954-ORF polypeptide in A549 cells had tumor growth-inhibitor features." (PMID 38351332, 2024). "Here, we report a novel LINC00954-derived polypeptide LINC00954-ORF that possesses tumor-suppressor features in A549 and A549/PEM LUAD cells." (PMID 38351332, 2024). "These may contribute to the LINC00954-ORF polypeptide’s tumor-suppressor features in A549 LUAD cells." (PMID 38351332, 2024).